KRAS (KRas proto-oncogene, GTPase)
Diseases named in the same sentence as KRAS in open-access papers (continued):
Sharing a sentence is not in itself a finding about the gene and the disease.
adenoma (continued). "In CRC, BRAF and KRAS alterations typically arise at the adenoma stage of the adenoma‐carcinoma sequence, following an initial APC alteration." (PMID 34584977, 2021). "In the first pathway, adenoma formation occurs in an MMR-proficient background, and carcinogenesis is characterized by APC and/or KRAS mutation and IGF2, NEUROG1, CDK2A, and/or CRABP1 hypermethylation." (PMID 34201893, 2021). "Similar to Lef1 deletion, oncogenic KRAS has been shown to induce Myc and Cd44 expression and increase the dedifferentiation of the adenomas." (PMID 34788095, 2021). "Previous studies have investigated the role of molecular markers in polyps for predicting the development of metachronous lesions, especially advanced adenomas, revealing an increased MACL risk in patients with KRAS-mutated polyps at baseline." (PMID 33440809, 2021). "In previous studies, somatic mutations in KRAS, BRAF, and PIK3CA have been found in CRC or adenomas from other germline gene mutation carriers." (PMID 34549727, 2021). "Sample AC6 was re-dissected into two adenoma regions (A1, A2) of different grades and two carcinomas (C1, C3) of different stages, with public mutations of APC, KRAS, and PLK1 found in all four regions." (PMID 32895052, 2020). "KRAS was reported to play driver roles during the progression from early to intermediate adenoma stages." (PMID 32117908, 2020). "In this group, 58 polyps were analyzed (41 tubular adenomas with low-grade dysplasia, 15 HP and 2 sessile serrated adenoma/polyps (SSA/p) and 13.8% were KRAS-mutated (n = 8/58) while 20.7% were BRAF-mutated (n = 12/58)." (PMID 32517177, 2020). "A subsequent mutation usually affects the Kirsten rat sarcoma viral oncogene homolog (KRAS) gene, which further enhances Wnt signaling and thereby facilitates the adenoma growth." (PMID 31614493, 2019). "For the 98 adenoma samples, BRAF mutation was observed in two cases, with an incidence of 2% (2/98), and KRAS mutation was detected in 23 cases, with an incidence of 23.5% (23/98)." (PMID 31690257, 2019). "The molecular analysis revealed that, in CRC, the classical adenoma-carcinoma sequence pathway is predominantly dominated by CIN and KRAS mutations." (PMID 30785889, 2019). "We detected a significantly low incidence of BRAF mutation in adenomas (2%) and CRC (0.7%), and a relatively low incidence of KRAS mutation (24.9%) compared with that in other populations." (PMID 31690257, 2019). "Surprisingly, we detected a significantly low incidence of BRAF mutation, both in adenomas (2%) and in CRC (0.7%), and a relatively low incidence of KRAS mutation (24.9%) compared with that in other populations." (PMID 31690257, 2019). "This study detected a significantly low incidence of BRAF mutation in adenomas (2%) and CRC (0.7%), and a relatively low incidence of KRAS mutation (24.9%) compared with that in other populations." (PMID 31690257, 2019).
adenoma (continued). "We also employed a ddPCR platform to seek KRAS and BRAF mutations in the plasma of patients bearing mutated adenomas." (PMID 30166531, 2018). "One study suggests combining conventional adenomas and LAMN into a single diagnostic category in part because of their high rates of KRAS and low rates of BRAF mutation; however, their capacity for peritoneal dissemination differs." (PMID 28591173, 2017). "Presence of APC, KRAS, NRAS, and GNAS mutations in HGCA well matched ‘classical adenoma-carcinoma model’." (PMID 28179590, 2017). "Our HGCA mutation list includes not only those in this classical model (APC and KRAS) but also those already known as adenoma genes (NRAS and GNAS)." (PMID 28179590, 2017). "Here we validate BaseScope ISMD technology and use it to map the topography of subclones bearing driver mutations in one of the KRAS, PIK3CA or BRAF proto-oncogenes in CRCs and adenomas." (PMID 29222441, 2017). "Generally, it has been seen that conventional adenomas follow the traditional pathway of developing cancer with CIN, CIMP-negative, MSS, BRAF wild type and KRAS mutated." (PMID 27902488, 2017). "A miR-31 transgenic mouse has increased lung hyperplasia, adenoma, and adenocarcinoma and promotes KRAS mediated oncogenesis by directly reducing expression of negative regulators of RAS/MAPK signaling." (PMID 27339092, 2016). "In adenomas, mutations in KRAS and BRAF occur in early to advanced adenomas in the adenoma-to-carcinoma sequence." (PMID 26910894, 2016). "Another genetic event conferring neoplastic properties to colonic cells was found to occur in the KRAS proto-oncogene in intermediate adenomas." (PMID 27279102, 2016). "In the step-wise genetic alteration model associated with colorectal tumorigenesis, PIK3CA mutations occur after KRAS or BRAF mutations and, in cooperation with other mutations, drive clonal evolution from large adenoma to invasive adenocarcinoma." (PMID 26498038, 2015). "Jass proposed that one of the molecular subtypes of CRCs that is characterized by CIMP-L, KRAS mutation and microsatellite stable/MSI-L, originates from adenoma or serrated polyps." (PMID 25289081, 2014). "A total of 19 canine gastric epithelial neoplasms (5 adenomas and 14 carcinomas) were retrospectively evaluated for EGFR/HER-2 immunohistochemical expression and KRAS mutational status." (PMID 24454858, 2014). "Among these genetic changes, different studies have shown that mutations in the KRAS gene were found in over 30% of CRC and advanced adenomas." (PMID 24720724, 2014). "Whereas CSCs are present in Apc/KRAS tumours, they appear to be very rare (<10−6) in the Apc–mutant adenomas." (PMID 24069241, 2013).
adenoma (continued). "Eleven samples, two adenomas, one serrated adenoma, four primary tumors and their matched metastases, were scored KRAS positive." (PMID 24280411, 2013). "KRAS mutations are believed to emerge early during CRC progression and are associated with the growth of small adenomas to a clinically significant size." (PMID 23226727, 2012). "A high combined mutation rate (79–82%) of KRAS and BRAF in serrated adenomas and adenocarcinomas indicates that mitogen-activated protein kinase activation is a crucial part of the serrated pathway." (PMID 21457162, 2011). "Either KRAS or BRAF mutation was observed in 85.7% of these cases, and in 82.4% of the serrated adenomas." (PMID 21457162, 2011). "The high rate of concordance is in agreement with the notion that KRAS mutations are considered as early driving events in CRC progression, and associated with the growth of small adenoma to clinically significant size." (PMID 21364579, 2011). "Both observations highlight the role of KRAS activation in the initiation of the different types of sporadic CRC besides its role in the adenoma-carcinoma multistep pathway of colorectal carcinogenesis." (PMID 18782444, 2008). "The three conventional adenomas with mutations of both BRAF and KRAS were among only four adenomas that had any BRAF mutations at all." (PMID 16879389, 2006). "KRAS mutation occurred more frequently (26.5%) than BRAF mutation (4.8%) in adenomas (P < 0.001) and particularly in adenomas with villous architecture (50%)." (PMID 16879389, 2006). "Targeting ACSS2 may be a promising therapeutic approach to target KRAS G12V mutant adenomas and/or early-stage CRC." (PMID 40131933, 2025). "•KRAS c.34G>T is a more accurate biomarker of biallelic MUTYH in CRCs than adenomas." (PMID 39793275, 2025). "A previous study on FAP tumors suggested that KRAS mutations were not necessary in APC-associated FAP adenomas, as codon 12 mutations are rarely (10%) observed." (PMID 41488735, 2025). "KRAS mutations are found in 40% of metastatic colorectal cancer, whilst BRAF mutations are only seen in 10–15% of metastatic disease, suggesting that the adenoma-carcinoma pathway has a greater metastatic potential." (PMID 39340753, 2024). "The observation that the KRAS mutation was absent in the normal mucosa was not controversial and supports current belief that KRAS-activating mutations occur later in the adenoma-carcinoma progression model, after APC driver mutations." (PMID 39507544, 2024). "Both adenomas in patient P2 harbored the same APC (Q1285X) and KRAS (G12S) mutations." (PMID 39554798, 2024). "Considering our new findings, it is also of interest to study the KRAS c.34G>T variant in serrated precursor lesions compared with conventional nonserrated adenomas." (PMID 39039804, 2024). "Four adenomas had both PIGA and KRAS mutations and were all TAs with LGD." (PMID 38546397, 2024). "In contrast, traditional serrated adenomas usually display low methylation, a stable microsatellite profile (MSS), may exhibit mutations in KRAS or BRAF, but are mostly characterized by their high level of TGFβ pathway activation." (PMID 37860822, 2023). "SuSA has been elucidated to be a precursor lesion of KRAS-type traditional serrated adenoma." (PMID 37273517, 2023).
adenoma (continued). "Activating KRAS mutations (KRAS-mut), chromosome 18 deletions that include the DCC locus, and inactivation of the TGF-β response by SMAD2/SMAD4 changes are key steps in the development of adenomas." (PMID 37296894, 2023). "According to molecular tests, presence of a residual adenoma component was correlated with a high frequency of the KRAS mutation (65%, p = 0.031) but not with MSI." (PMID 36083889, 2022). "MBD4-deficient adenomas harbored fewer KRAS mutations (three of 19 adenomas) than sporadic tumors (Fisher’s exact, p = 0.0028) but significantly more somatic mutations in AMER1 (MIM: 300647) (12 of 19 adenomas; Fisher’s exact, p = 0.039)." (PMID 35460607, 2022). "KRAS (G12D) mutation in AT2 cells generates multifocal, clonal adenomas in transgenic mice." (PMID 32771979, 2020). "Moreover, when inactivation of RhoA signaling by transducing dominant-negative form of RhoA resulted in larger adenomas and decreased survival in a zebrafish model of KRAS-induced hepatic adenoma by rising AKT/S6 signaling and cyclin D1." (PMID 32244355, 2020). "KRAS and APC mutations have also been identified in aberrant crypt foci in the colon which may be precursors of adenomas and CRC." (PMID 32380676, 2020). "KRAS mutations were found in the plasma of 3/19 patients with high-grade intraepithelial neoplasia (15.8%), 1/54 patients with adenomas (1.8%), and none of the patients with hyperplasia." (PMID 32380676, 2020). "Intake of vitamin B2 was somewhat positively, but not significantly, associated with KRAS+ adenomas." (PMID 32723394, 2020).
adenoma (continued). "Somatic analysis of DNA from affected adenomas showed G > T changes at KRAS locus (ID 89)." (PMID 31285513, 2019). "The last subtype of CRC may develop from both conventional adenoma and sessile serrated adenoma, includes about 20% of tumors, and is characterized by CIN, CIMP-L, MSS, or MSI-L due to MGMT methylation, and always KRAS mutations." (PMID 31803624, 2019). "Epigenetic silencing of SMOC1 may be associated with the development of KRAS mutant, CIMP-low and MSS CRCs derived from TSAs or conventional adenomas." (PMID 29435136, 2018). "However, the monoclonal origin of CRC has been brought into question by genetic analysis of individual colonic crypts of benign adenomas, in which polyclonality of driver events, including distinct mutations in APC and KRAS, has been identified." (PMID 30166531, 2018). "SMOC1 methylation-positive adenomas and cancers were associated with frequent KRAS mutation and a lack of MLH1 methylation." (PMID 29435136, 2018). "This pathway is thought to be distinct from the conventional adenoma-carcinoma pathway, where adenomas progress to invasive colorectal carcinomas through the influence of several genetic alterations including adenomatous polyposis coli (APC) and KRAS mutations." (PMID 30458818, 2018). "Recently, ACF were identified in the proximal colons of about 40% of individuals undergoing high-resolution chromoendoscopy and more frequently in patients with synchronous proximal adenomas; somatic mutations of APC, BRAF, KRAS, NRAS and ERBB2 were detected in 37% of proximal ACF." (PMID 29652830, 2018). "However, patients in the KRAS group developed advanced polyps (log-rank 0.037) and, more specifically, advanced adenomas (log-rank 0.010), at higher rates than patients in the WT group." (PMID 28953955, 2017). "Mutant KRAS may, in part, drive the histologic progression of adenomas toward villous histology and higher grades of dysplasia." (PMID 26910894, 2016). "In the classical path of CRC development, activating mutations in the KRAS oncogene are thought to follow aberrant WNT pathway activation; hence, the origin of the TA1 organoid culture is likely to be a more advanced adenoma or early carcinoma." (PMID 27221051, 2016). "KRAS and BRAF mutations occur relatively early in the adenoma-carcinoma process." (PMID 26910894, 2016). "The characteristic distribution of KRAS and BRAF mutations suggest there may be two different pathways in adenoma to adenocarcinoma progression." (PMID 26910894, 2016). "The molecular mechanisms underlying the adenoma-carcinoma sequence has been extensively studied and involves a cumulative acquisition of mutations in tumor suppressor genes, such as APC, and oncogenes such as KRAS and BRAF, leading to genomic instability." (PMID 26910894, 2016). "The frequency of KRAS-mutation(+) did not increase significantly in cancer compared with that in adenoma and a significant correlation between intermediate-methylation and KRAS-mutation(+) was already detected at the adenoma stage." (PMID 27563825, 2016). "In the adenoma-carcinoma sequence, the proliferative hormonal exposure in the presence of ERα and the decrease of ERβ could be a factor to select KRAS mutant clones in the adenocarcinoma histologic subtype in females." (PMID 24720724, 2014).